NUDT5 (nudix hydrolase 5)
Diseases named in the same sentence as NUDT5 in open-access papers (continued):
Sharing a sentence is not in itself a finding about the gene and the disease.
tumor (11 papers, 2017 to 2025). "We observed that silencing NUDT5 resulted in significantly reduced tumor growth, with decreased tumor size and weight compared to the control group." (PMID 40426963, 2025). "Next, to investigate the role of upregulated NUDT5 on EC in vivo, we established a xenograft tumor model with HEC-1B cells overexpressing NUDT5." (PMID 40426963, 2025). "Xenograft TNBC animal models were employed to assess the effect of NUDT5 inhibition on in vivo tumor growth." (PMID 38317231, 2024). "In both in vitro and in vivo settings, our investigations revealed that the NUDT5 inhibitor significantly suppresses TNBC tumor growth." (PMID 38317231, 2024). "To further evaluate the performance of the screen, we assessed the enrichment of gRNAs targeting well-characterised 6-TG sensitivity genes HPRT1 and NUDT5, as well as those in the mismatch repair pathway, in treated tumours." (PMID 37684549, 2023). "Our results suggested that the overexpression of MTH1 and NUDT5 is probably involved in the tumor development and poor prognosis of ESCC." (PMID 32518727, 2020). "Our present study aims to explore their prognostic value in ESCC and investigate their function in MTH1 or NUDT5-knockout tumor cells." (PMID 32518727, 2020). "Immunohistochemical analyses of TMAs verified that MTH1 and NUDT5 proteins were highly expressed in tumor tissues." (PMID 32518727, 2020). "A Western blotting analysis of MutT-related proteins in 20 paired CRC samples and adjacent normal tissues showed that the expression of MTH1, MTH2, MTH3 and NUDT5 was significantly upregulated in tumor tissues." (PMID 29285286, 2017). "Focusing on the role of NUDT5 in EC, we found that upregulated NUDT5 mRNA and protein expression levels correlated positively with more advanced histological grades, suggesting a more aggressive tumor phenotype." (PMID 40426963, 2025). "Investigating NUDT5’s function in EC could provide new insights into the molecular mechanisms driving tumor progression and identify therapeutic opportunities." (PMID 40426963, 2025). "We observed that the overexpression of NUDT5 significantly promoted tumor growth." (PMID 40426963, 2025). "Furthermore, treating nude mice bearing NUDT5-overexpressed xenograft tumors with Perifosine reversed these effects, indicating that inhibition of the AKT counteracts NUDT5-induced tumor growth." (PMID 40426963, 2025). "Moreover, NUDT5 overexpression enhanced EC cell migration and invasion, indicating its role in promoting tumor metastasis." (PMID 40426963, 2025). "In earlier studies, NUDT5 has been implicated in ADP-ribose metabolism, which plays a key role in maintaining genomic stability and DNA damage response, processes that are crucial for tumor progression." (PMID 40426963, 2025). "Our data also suggest that NUDT5 may influence epithelial–mesenchymal transition, a critical step in tumor metastasis." (PMID 40426963, 2025). "Furthermore, we demonstrated the potent tumor growth inhibitory properties of the NUDT5 small molecule inhibitor, TH5427, both in vitro and in vivo." (PMID 38317231, 2024). "NUDT5 was found to be upregulated in tumors compared with paired adjacent non-tumor tissues." (PMID 33571243, 2021). "MTH1 and NUDT5 protein expression in ESCC adjacent normal tissues and tumor tissues was examined by immunohistochemistry staining." (PMID 32518727, 2020). "We have shown that elevated levels of NUDT5 and, specifically, ATP enzymatic activity are essential in driving the expression of known CSC and EMT genes, as well as novel tumour drivers detected using the 3D oncosphere model." (PMID 31510016, 2019). "Weighted gene co-expression network analysis (WGCNA) and experimental validation were performed to explore the impact of NUDT5 on the PI3K-AKT signaling pathway, while tumor growth assays in xenograft models assessed the therapeutic potential of NUDT5 inhibition in vivo." (PMID 40426963, 2025). "Mechanistically, NUDT5 activated the PI3K-AKT pathway, contributing to tumor progression." (PMID 40426963, 2025).
NUDT5 also shares sentences with these, for which no sentence is quoted: esophageal squamous cell carcinoma (2 papers); glioma (2); bacterial infection (1); breast adenocarcinoma (1); clear cell renal cell carcinoma (1); COVID-19 (1); frontal lobe epilepsy (1); lung carcinoma (1); metastasis (1); non-small cell lung carcinoma (1); ovarian carcinoma (1); triple-negative breast carcinoma (1).